DACH1 (dachshund family transcription factor 1)
Diseases named in the same sentence as DACH1 in open-access papers (continued):
Sharing a sentence is not in itself a finding about the gene and the disease.
diabetic nephropathy (3 papers, 2018 to 2023). "GWAS analysis showed that loss of DACH1 function was a susceptibility factor for renal fibrosis, and DACH1 can protect against podocyte damage in diabetic nephropathy model mice." (PMID 36875100, 2023). "To analyse the regulation of DACH1 in diabetic nephropathy (DN), we assessed the mRNA expression level of DACH1 in microdissected glomeruli from renal biopsies of patients suffering from DN (n = 7) and compared them with healthy LD (n = 18)." (PMID 29498212, 2018). "Podocyte-specific overexpression of DACH1 protects mice from diabetic kidney disease." (PMID 36750914, 2023). "Interestingly, glomeruli of biopsies from patients suffering from diabetic nephropathy showed also a significant reduction of Dach1 and synaptopodin in contrast to control biopsies." (PMID 29498212, 2018).
glomerular disease (3 papers, 2016 to 2023). "The current study aims to clarify the immunological characteristics and the function of DACH1 protein associated with disease progression in glomerulopathy by means of immunohistology." (PMID 27888806, 2016). "Detailed cellular expression pattern and function of DACH1 in adult human kidney and the relationship between the expression of DACH1 and clinic-pathological characteristics in glomerular diseases have yet to be reported." (PMID 27888806, 2016). "Together, These findings indicate that DACH1 expression is decreased in glomerulopathy imply a potential role for DACH1 in the this development of human chornic glomerulopathy." (PMID 27888806, 2016). "Taken together, it can be deduced that DACH1 is a potential marker of disease severity and disease progression in glomerulopathy." (PMID 27888806, 2016). "In conclusion, the results of our study suggest that DACH1 expression is decreased in glomerulopathy and involved in regulating cell cycle-related proteins imply a potential role for DACH1 in the this development of human chornic glomerulopathy." (PMID 27888806, 2016). "For initial characterization of DACH1 staining in diseased kidney tissues, we examined renal biopsies from glomerular disease." (PMID 27888806, 2016). "Further analysis of DACH1 staining in renal glomerulus among normal kidney tissue and different types of glomerulopathy tissues showed that normal cells exhibited the highest DACH1 expression (p < 0.001)." (PMID 27888806, 2016). "Toghter, these data suggest that DACH1 is a potential a marker of disease progression and severity for glomerular diseases." (PMID 27888806, 2016). "To find out whether the Dach1 expression is also altered in patients suffering from glomerular disease, we measured the DACH1 mRNA expression of microdissected glomeruli and co‐stained biopsies for DACH1 and synaptopodin." (PMID 29498212, 2018). "Furthermore, our findings are in line with a recent publication reporting a positive correlation between glomerular DACH1 staining and the estimated glomerular filtration rate in patients suffering from glomerulopathy." (PMID 29498212, 2018). "Many of the transcription factors have previously been shown to play a role in podocyte injury and glomerular disease, such as MAFB, TCF21, DACH1 and the recently reported FOXC1." (PMID 37681897, 2023). "DACH1 staining occasionally was found in renal interstitium of diseased samples with glomerulopathy accompanied by chronic renal lesion, but was absent from the renal interstitium of normal tissue." (PMID 27888806, 2016). "Glomerular DACH1 expression levels were the highest in normal renal tissue, obviously higher than in the IgAN, IMN, and MCD, the three most common renal histopathologic patterns among the entire spectrum of primary glomerular diseases." (PMID 27888806, 2016).
Nephropathy (3 papers, 2016 to 2023). A nonspecific term referring to disease or damage of the kidneys. "Moreover, tubule-specific DACH1-knockout mice were more susceptible to renal damage and fibrosis in a FA-induced nephropathy model." (PMID 36875100, 2023). "In the present study, we found a marked decrease in DACH1 protein expression in human nephropathy, especially in glomerulus." (PMID 27888806, 2016). "There was more positive DACH1 immunostaining in normal renal glomerulus and kidney tubules than in nephropathy tissues (p < 0.05) and more severe renal pathological lesions were associated with less glomerular and tubular DACH1 expression." (PMID 27888806, 2016). "We found that DACH1 expression was decreased in the nephropathy group relative to healthy controls." (PMID 27888806, 2016). "In normal cases, no evident DACH1 staining was observed in renal interstitium, but in nephropathy tissues with obvious renal lesions, intermittent staining was shown in the area." (PMID 27888806, 2016).
non-small cell lung carcinoma (3 papers, 2019 to 2025). A group of at least three distinct histological types of lung cancer, including non-small cell squamous cell carcinoma, adenocarcinoma, and large cell carcinoma. "For instance, the DACH1 methylation rate was illustrated higher levels in non-small cell lung cancer compared to adjacent normal lung tissues and demethylation treatment contributed to decreased migration and invasion of cancer cells." (PMID 40370966, 2025). "In a search for lung tumor suppressor by genomic landscape, DACH1 was described as a potential tumor suppressor in non-small cell lung cancer (NSCLC)." (PMID 31998654, 2019). "The relationship between CXCL1 and DACH1 in non-small cell lung cancer (SCLC) deserves further investigation." (PMID 31998654, 2019).
Obesity (3 papers, 2014 to 2023). Accumulation of substantial excess body fat. "In an adequately powered case-control cohort of familial YOD characterized by obesity, we discovered several common SNPs (allele frequency>0.3) with ORs of 2–2.5, including the T allele of rs1408888 of DACH1 with allele frequency of 0.75 and an OR of 2.49." (PMID 24465431, 2014). "Thus, hepatocyte DACH1 emerges as an important link between obesity-associated metabolic stress and impaired fibrinolysis." (PMID 32657780, 2020). "Given the rapid westernization of Hong Kong Chinese within less than a century, we hypothesize that DACH1 may be a thrifty gene which regulates growth to improve survival chances during time of hardship but increases risk of obesity, prediabetes, YOD and CVD during time of affluence." (PMID 24465431, 2014). "Increased hepatocyte DACH1 in obesity limits the rise in tPA and thereby contributes to impaired fibrinolysis." (PMID 32657780, 2020). "In summary, the increase in hepatocyte tPA in obesity is limited by the counteracting process of DACH1-mediated Plat repression, and the resulting net level of hepatic tPA expression is not high enough to overcome PAI-1–mediated impaired fibrinolysis." (PMID 32657780, 2020). "Having elucidated a factor that lowers hepatocyte tPA in obesity, i.e., the increase in DACH1, we next sought to understand the counteracting mechanism that causes the net increase in hepatocyte and plasma tPA in obesity." (PMID 32657780, 2020). "We reasoned that this pathway would be particularly relevant to obesity, as hepatocyte DACH1 is increased in the livers of obese mice and humans, which we verified here." (PMID 32657780, 2020). "A study based on insulin resistance reported that CaMKII phosphorylates and blocks nuclear translocation of hepatocyte HDAC4 under conditions of obesity: lower nuclear HDAC4 decreases the SUMOylation and degradation of the co-repressor DACH1, and finally, causes defective insulin signaling." (PMID 37766305, 2023). "Interestingly, we showed previously that increased hepatocyte DACH1 in obesity also promotes excessive hepatic glucose production." (PMID 32657780, 2020). "This response may then become compromised by disease-related processes, as exemplified by the elevation of DACH1 in hepatocytes in obesity, which decreases tPA expression and thereby limits the compensatory response." (PMID 32657780, 2020). "Although this tPA response pathway is partially counteracted by a coexisting tPA-suppressive pathway mediated by the corepressor DACH1, we provide evidence that the PAI-1/tPA pathway limits the degree of impairment of fibrinolysis in obesity." (PMID 32657780, 2020). "In insulin resistance induced by obesity in mice, it was found that obesity can activate CaMK II, which induced HDAC4 phosphorylation and prevented its nuclear translocation, resulting in a decrease in DACH1 expression level." (PMID 37766305, 2023).
osteosarcoma (3 papers, 2016 to 2021). A usually aggressive malignant bone-forming mesenchymal neoplasm, predominantly affecting adolescents and young adults. "Additionally, a recent study claimed that cytoplasmic and nuclear expression of DACH1 involved in cell proliferation in osteosarcoma; for instance, cytoplasmic DACH1 might promote cell proliferation." (PMID 27888806, 2016).
renal fibrosis (3 papers, 2023 to 2024). A final common manifestation of a wide variety of chronic kidney diseases characterized by glomerulosclerosis and tubulointerstitial fibrosis. "Similarly, DACH1, which was associated with eGFRcr, eGFRcys, and BUN in our study, was previously studed in murine models that demonstrated tubule-specific Dach1 deletion caused more severe renal fibrosis after kidney injury." (PMID 37365616, 2023). "In contrast, distal tubule-specific Dach1 overexpression attenuated renal fibrosis induced by folic acid injection." (PMID 38805434, 2024). "After injection with folic acid or injection with streptozotocin and heminephrectomy, Dach1 KO mice showed severe renal fibrosis." (PMID 38805434, 2024).
breast neoplasm (2 papers, 2017). A benign or malignant neoplasm of the breast parenchyma. "Breast tumors with positive ER–alpha and co-expressing PR-alpha were most likely to highly express DACH1, and nuclear DACH1 expression was positively correlated with luminal marker FOXA1 and inversely associated with basal-like markers EGFR13." (PMID 28659634, 2017). "Our results supported that luminal breast neoplasm tended to be with high DACH1 expression and low CD44 level, while basal-like tumors were most likely to be the inverse type." (PMID 28659634, 2017). "Dachshund homolog 1 (DACH1), a key cell fate determination factor, contributes to tumorigenesis, invasion, metastasis of human breast neoplasm." (PMID 28659634, 2017).
clear cell renal carcinoma (2 papers, 2014 to 2017). A malignant epithelial neoplasm of the kidney characterized by the presence of lipid-containing clear cells within a vascular network. "In the search for novel epigenetic markers for clear cell renal cell carcinoma, Dr. Dalgin’s group found DACH1 was among the 6 down-regulated genes with hypermethylation of promoter region." (PMID 25322986, 2014). "Epigenetics changes in 38 matched renal clear cell carcinoma and normal tissues demonstrated that DACH1 promoter region was hypermethylated in renal cell carcinoma." (PMID 25322986, 2014). "Restoration of DACH1 function in renal clear cell cancer cells inhibited in vitro cellular proliferation, S phase progression, clone formation, and in vivo tumor growth." (PMID 25322986, 2014). "Restoration of DACH1 function in renal clear cell cancer cells inhibited in vitro cellular proliferation and in vivo tumor growth." (PMID 25322986, 2014).
COVID-19 (2 papers, 2021 to 2023). A disease caused by infection with severe acute respiratory syndrome coronavirus 2. "This novel technology has been used successfully in several organs—for example, to study Prominin 1+ liver progenitors, Dach1–downregulated lymphoid progenitors and KTR5+ lung progenitors in COVID-19 patients." (PMID 33401654, 2021).
endometrioid tumor (2 papers, 2019). A benign, borderline, or malignant epithelial tumor of the female reproductive system characterized by the presence of glands and/or cysts lined by neoplastic cells that resemble endometrial cells. "Consistent with our previous study, DACH1 was downregulated in papillary serous tumor and endometrioid tumor." (PMID 31215145, 2019). "ANO1, SOX17, CGNL1, DACH1, RUNDC3B, SH3YL1 and CRISPLD1 were significantly downregulated both in papillary serous tumors and endometrioid tumor." (PMID 30813939, 2019).
glioblastoma (2 papers, 2014 to 2023). The most malignant astrocytic tumor (WHO grade IV). "DACH1 probably regulates temozolomide resistance in glioblastoma through the transcriptional dysregulation in cancer and ECM." (PMID 36959804, 2023).
Glomerular sclerosis (2 papers, 2023 to 2024). Accumulation of scar tissue within the glomerulus. "This may challenge the causal role of Dach1 deficiency to glomerulosclerosis." (PMID 38805434, 2024). "Mechanically, we speculated that the low expression of DDX17 might further down-regulate the activity of TCF21 and DACH1, worsen the glomerular sclerosis and renal interstitial fibrosis." (PMID 36875100, 2023). "Thus, Dach1-positive podocytes do not lead to glomerulosclerosis but are involved in the sclerotic lesions caused by adjacent Dach1-deficient podocytes." (PMID 38805434, 2024).
Hyperglycemia (2 papers, 2023). An increased concentration of glucose in the blood. "In DACH1 knockdown podocytes combined with hyperglycemia, DACH1-PTIP promoter binding was reduced, transcriptional repression was lost, and the H3K4me3 expression level was increased." (PMID 37455912, 2023).
idiopathic membranous nephropathy (2 papers, 2016 to 2023). "Immunohistochemical staining of DACH1 proteins in human renal biopsies of immunoglobulin A nephropathy (IgAN) and idiopathic membranous nephropathy (IMN) patients show significantly decreased eGFR with declining DACH1, and significantly increased urinary protein in IMN with increasing DACH1." (PMID 36659918, 2023).
Insulin resistance (2 papers, 2014 to 2023). Increased resistance towards insulin, that is, diminished effectiveness of insulin in reducing blood glucose levels. "In this multi-staged experiment, we have discovered risk association of an intronic SNP (rs1408888) of DACH1 with YOD, BP, insulin resistance and CVD in Chinese populations." (PMID 24465431, 2014).
kidney cancer (2 papers, 2016 to 2023). Primary or metastatic malignant neoplasm involving the kidney. "DACH1, a known tumor suppressor gene in breast, colon, and kidney cancers, plays a key role in tumor growth and metastasis by acting on cell cycle control." (PMID 36769068, 2023). "This is consistent with our previous work, which reported that DACH1 level is inversely correlated with PCNA expression and that it inhibits cellular proliferation in kidney cancer." (PMID 27888806, 2016).
leukemia (2 papers, 2016 to 2024). A malignant (clonal) hematologic disorder, involving hematopoietic stem cells and characterized by the presence of primitive or atypical myeloid or lymphoid cells in the bone marrow and the blood. "Of the upregulated genes, Syne1, Atxn10 and Dach1 show activation as early as Day 11, while Ngp, Abca13, Adpgk, Mmp8 and Lcn2 were more significantly upregulated in the later stage, D14 neutrophils,which suggests a sequential activation in Camk1d + neutrophils during leukemia progression." (PMID 38730491, 2024).
oral carcinoma (2 papers, 2015 to 2018). "DACH1 was found to be the less frequent methylation in oral carcinoma cell lines as the negative regulator of Wnt pathway." (PMID 30261897, 2018).
prostatic intraepithelial neoplasia (2 papers, 2023). "In prostate OncoMice, prostate-specific deletion of the Dach1 gene enhanced prostatic intraepithelial neoplasia (PIN), and was associated with increased TGFβ activity and DNA damage." (PMID 37095257, 2023).
pulmonary fibrosis (2 papers, 2025). Chronic progressive interstitial lung disorder characterized by the replacement of the lung tissue by connective tissue, leading to progressive dyspnea, respiratory failure, or right heart failure. "LncRNA DACH1 is significantly down-regulated in the lungs of patients with IPF as well as in experimental mouse models of pulmonary fibrosis." (PMID 40782499, 2025). "For example, DACH1 (LncRNA) can inhibit the activation of lung fibroblasts and the excessive deposition of the ECM by binding to SRSF1 and suppressing the expression of SRSF1 and CTNNB1 proteins, which helps alleviate pulmonary fibrosis." (PMID 40427668, 2025).
Type 2 diabetes (2 papers, 2013 to 2014). "Meta-analysis of risk association of DACH1 rs1408888 with Type 2 diabetes in independent multi-ethnic Asian case-control cohorts." (PMID 24465431, 2014).
uterine cancer (2 papers, 2014 to 2020). Primary or metastatic malignant neoplasm involving the uterine corpus and/or the cervix. "We identified 3.8% (25/586 patients) DACH1 gene mutations in uterine cancer somatic samples in the TCGA PCA of endometrial and carcinosarcoma patients, which was significantly lower than the 18.5% (12/65, p = 1.05E-05) seen in the MCC patient cohort." (PMID 33378353, 2020). "Loss of DACH1 expression is associated with poor prognostic features and reduced overall survival in uterine cancer." (PMID 33378353, 2020). "DACH1’s putative tumor suppressive function has also been documented in studies of breast, prostate, and uterine cancers, where its expression was found to be frequently downregulated." (PMID 24472434, 2014).
acute myeloid leukemia (1 paper, 2023). Acute myeloid leukemia (AML) is a group of neoplasms arising from precursor cells committed to the myeloid cell-line differentiation. "Previous studies have shown that in acute myeloid leukemia with RUNX1 mutations, DACH1 mRNA expression is upregulated after RUNX1 mutations occur." (PMID 37766305, 2023).
atherosclerosis (1 paper, 2022). A disease characterized by the build-up of fatty material and calcium deposition in the arterial wall resulting in partial or complete occlusion of the arterial lumen. "An interaction between miR-484 and DACH1 was found, which should be further explored in atherosclerosis and vulnerable plaques." (PMID 36139031, 2022).
Brain Tumor (1 paper, 2023). "We found DACH1 mutations (mainly inframe deletions) and DNA methylation in some patients while investigating the Brain Tumor PDXs (Mayo Clinic, Clin Cancer Res 2020) dataset on the cbioportal website." (PMID 36959804, 2023).
Branchio-oculo-facial syndrome (1 paper, 2016). "DACH1 is a candidate gene for branchio-oculo-facial syndrome and Fraser syndrome based on the phenotypic presentation." (PMID 27888806, 2016).
Cachexia (1 paper, 2022). Severe weight loss, wasting of muscle, loss of appetite, and general debility related to a chronic disease. "Of the six proteins that showed significant differences between the patients with and without cachexia, three were lower (CNPD1, APOA4, DACH1) while three were higher (BCL3 NARS2, ATP13A4) in cachexia." (PMID 36080280, 2022).
chronic hepatitis (1 paper, 2015). An active inflammatory process affecting the liver for more than six months. "No statistical significance was found for DACH1 expression in cirrhosis, steatosis, chronic hepatitis and normal tissue (f test, p = 0.194)." (PMID 25940701, 2015). "In order to comprehend the significance of DACH1 expression in liver benign as well as malignant lesions, we analyzed DACH1 protein levels in a TMA containing 120 informative patients with various hepatic lesions, which mainly included cirrhosis, steatosis, chronic hepatitis, hemangioma and cancer." (PMID 25940701, 2015).
Conn’s syndrome (1 paper, 2015). "CNVs of glycine-repeat deletions in DACH1 discovered by our previous exome sequencing were validated and confirmed by Sanger Sequencing of the DNA from APAs and the adjacent adrenal glands (AAG) and from the blood of both patients with Conn’s syndrome and healthy controls." (PMID 25776071, 2015).
developmental delay (1 paper, 2025). "Other candidate AD genes include DACH1, KCTD12, KLF5, and RBM26, all of which have been implicated in syndromic developmental delay, neuropsychiatric traits, or cancer predisposition based on case reports or CNV analyses." (PMID 40978814, 2025).